IL6 (interleukin 6)
Diseases named in the same sentence as IL6 in open-access papers (continued):
Sharing a sentence is not in itself a finding about the gene and the disease.
gastric cancer (continued). "Concomitant expression of IL-6 and SOCS-1 can be observed in most gastric cancer cell lines, except KATOIII and AGS cell." (PMID 15354212, 2004). "Studies have shown that down-regulating IL-6, IL-17RA and tumor necrosis factor-alpha (TNF-α) levels can effectively improve the pathological changes of gastric mucosa tissue and hinder the development of PLGC into gastric cancer." (PMID 41284643, 2025). "In patients with gastric cancer at stage IV of the disease, multidirectional changes occur when studying proinflammatory cytokines: a decrease in TNF-α, IL-8, TNF-β, as well as an increase in IL-2, IFNγ, IL-17A, and IL-6." (PMID 40806737, 2025). "Although IL‐6 and interleukin 18 were detected as SASP proteins, their levels were not affected by PITX2‐mediated lysosomal exocytosis, suggesting the involvement of alternative mechanisms in regulating SASP in gastric cancer." (PMID 40995693, 2025). "An increase in the expression of RIPK2 facilitates resistance to innate and adaptive immune therapeutic techniques via pathways such as the IL-6/JAK/STAT3 signaling pathway, the interferon-γ response, and the interferon-α response; thus, RIPK2 plays an important role in gastric cancer." (PMID 39309860, 2024). "Albumin (ALB), B-cell lymphoma 2 (BCL-2), nuclear factor kappa B subunit 1 (NFKB1), hypoxia-inducible factor 1 alpha (HIF1A), and interleukin 6 (IL-6) had a higher expression in gastric cancer than in normal conditions." (PMID 39816318, 2024). "This is consistent with the results of previous studies that added GLP that 400 mg/kg GLP reduced serum levels of IL-1β and IL-6 in diabetic rats, and 800 mg/kg GLP reduced serum IL-6 and TNF-α levels and increased serum IL-2, IL-4, and IL-10 levels in rats with gastric cancer." (PMID 39457856, 2024). "Loss of AQP3 might lead to reduced expression of inflammatory factors like IL-6 and TNF-α, and AQP3 inhibition could decrease the production of IL-6, IL-1β, and TNF-α, impairing intestinal bacteria clearance and contributing to gastric cancer progression." (PMID 39060229, 2024). "The triad of “IL-6+p-Stat3+PD-1+ cell differentiation” is a key indicator of survival and is more reliable than the traditional TNM classification in determining postsurgical gastric cancer prognosis." (PMID 39309860, 2024). "Moreover, IL-6 can be secreted by inflammatory cells and cancer-associated fibroblasts (CAFs) in the hypoxic TME, favoring the activation of IL-6/JAK/STAT, EMT promotion, and gastric cancer cells’ invasion." (PMID 38069210, 2023). "Using the GTEx database, the expression level of IL-6 was positively correlated with PDL1 expression and M2 macrophage biomarkers, namely, CD206 and CD204, indirectly supporting the idea that IL-6 regulates immune function in gastric cancer." (PMID 38001573, 2023). "Besides, IL-6 and TNF-α secreted from macrophages induce PD-L1 expression through NF-κB and STAT3 signaling pathways in gastric cancer cells." (PMID 36978108, 2023). "Furthermore, the levels of IL-6, IL-10, TNF-α, and VEGF in the gastric cancer cell line were higher than those in normal human gastric mucosal epithelial cells." (PMID 36618075, 2022). "A meta-analysis showed that ω-3 PUFAs could improve the nutritional status of patients after gastrectomy of gastric cancer and downregulate the levels of inflammatory indicators, such as C-reactive protein (CRP) and interleukin 6 (IL-6)." (PMID 35910071, 2022). "The pro-inflammatory cytokines IL-1β, TNF, and IL-6 can induce the transition of EMT in head and neck cancers and anti-inflammatory cytokine IL-10 can lead to tumor cell proliferation through an induction of STAT3 activation in gastric cancer cells." (PMID 35283421, 2022).
gastric cancer (continued). "IL-6 can induce cell growth and VEGF synthesis in malignant mesotheliomas or gastric cancer." (PMID 35252204, 2022). "Chemerin may induce pro-invasive action in gastric cancer through induction of VEGF and other factors such as matrix metalloproteinases and Il-6." (PMID 34946244, 2021). "IL-6 enhances cancer cell growth and VEGF synthesis in gastric cancer and malignant mesotheliomas." (PMID 34445479, 2021). "The enrichment included the PI3K-Akt and IL-17 signaling pathways, and the network analysis showed that the Zhishi-Baizhu herb pair acted on seven key targets, namely, AKT1, MMP9, IL-6, CCND1, BCL2, MTOR, and MDM2 (where they played a role in treating gastric cancer)." (PMID 34899944, 2021). "For example, in gastric cancer cells, PPIs have been shown to inhibit the expression and nuclear translocation of hypoxia-inducible factor 1 α (HIF-1α), Wnt/β-catenin signaling, and the IL-6/STAT3 signaling pathway." (PMID 34262645, 2021). "Interestingly, miR-149 has been shown to be involved in tumor progression by regulating the interleukin-6 (IL-6)/signal transducer and activator of transcription 3 (STAT3) pathway in esophageal and gastric cancer." (PMID 32455867, 2020). "In addition, IL‐6 produced by CAF has been shown to support stemness of different CRC cell lines and induce resistance to chemotherapy in gastric cancer." (PMID 32767843, 2020). "IL-6 and IFN-γ cytokines may play a critical role in the development of gastric inflammation and later gastric cancer." (PMID 32231118, 2020). "Interestingly, we also found that proinflammatory cytokines (IL-6, IL-11) were rapidly induced after carcinogen exposure and maintained a high level in NOC-transformed and gastric cancer cells." (PMID 32041943, 2020). "Previous studies have shown that IL-6 is closely related to gastric cancer, but its correlation with DYNC1I1 has no reports yet." (PMID 31249807, 2019). "Collectively, these data revealed an important role for the DYNC1I1-driven IL-6/STAT pathway in gastric cancer proliferation and migration, suggesting that DYNC1I1 may be a potential therapeutic target for gastric cancer." (PMID 31249807, 2019). "In addition, knockdown of IL-6 reduced the migration of HGC-27 and SGC-7901 gastric cancer cells by about 45.2 and 37.4%, respectively (P < 0.05, both cell lines)." (PMID 31249807, 2019). "In gastric cancer cells, even the regulatory effects of IL-6/JAK/STAT3 on expression of pro-EMT TFs and EMT markers relied on NOX4, indicating the potential comprehensive role of ROS in the transduction of NF-κB/IL-6 signaling." (PMID 31849690, 2019). "High plasma level of IL-6, IL-8, and TGF-β1 were predictors of gastric cancer progression." (PMID 29742685, 2018). "We show that CAFs derived-IL-6 promoted the migration and EMT of gastric cancer cells via the activation of JAK2-STAT3 pathway, and blocking this pathway with IL-6 neutralizing antibody or JAK2 specific inhibitor AG490 impaired gastric cancer metastasis induced by CAFs in vivo." (PMID 28186964, 2017). "In contrast, adding IL-6 neutralizing antibody or JAK-2 protein tyrosine kinase inhibitor AG490 into the co-culture system significantly reversed CAF-mediated phosphorylation of JAK2 and STAT3 in gastric cancer cells." (PMID 28186964, 2017). "IL-6 and TNF are expressed at high levels in human gastric cancer samples." (PMID 28350359, 2017). "Moreover, in patients with gastric cancer, PMP level is a better prognostic indicator than IL-6 or VEGF." (PMID 27629289, 2016). "Analysis of the expression profiles of cytokines revealed that, regardless of the IL-6 levels being increased in the IL-6-hUC-MSCs, this did not induce a growth-promoting effect on gastric cancer." (PMID 25483835, 2015). "Anti-IL-6 neutralizing antibody did not affect the growth of any of the gastric cancer cells cultured alone, but it inhibited the growth of MKN-7, MKN-28, and MKN-74 cells co-cultured with Hs738 cells." (PMID 25785838, 2015).
gastric cancer (continued). "Gastric cancer cells secreted at least PGE2 and TNFα to stimulate IL-6 production by stromal cells." (PMID 25785838, 2015). "Actually IL-6 increased the growth of all the gastric cancer cell lines except MKN-45; in contrast, CXCL1 did not affect their growth." (PMID 25785838, 2015). "Thus, some of the gastric cancer cells secreted PGE2 and TNFα stimulating the stromal cells to secrete IL-6 that supported the growth of cancer cells." (PMID 25785838, 2015). "Moreover, gastric cancer cells secreted PGE2 and TNFα that stimulated IL-6 secretion by the stromal cells." (PMID 25785838, 2015). "In contrast, the stroma was positively stained for IL-6 expression in none of healthy controls, 40% of gastritis cases, 20% of gastric adenoma, and 74.2% of gastric cancer cases." (PMID 23593346, 2013). "IL-6, NF-κB and VEGF increased significantly in gastric cancer tissue, suggesting that high protein levels of NF-κB might be positively correlated with IL-6 protein levels." (PMID 23117246, 2013). "Moreover, IL-6 and STAT3 downstream signals such as IL-10 and VEGF were reduced in patients after removal of gastric cancer as compared to pre-operation." (PMID 24116074, 2013). "In addition, the expression of IL-6, survivin, STAT3, p-STAT3, and VEGF were increased in human gastric cancer tissues as compared to adjacent normal mucosa." (PMID 24116074, 2013). "The advancement stage of gastric cancer, which is correlated with a decrease in IL-6 and IL-23 levels does not seem to bear any relation to the number of platelets or their morphological parameters." (PMID 23554823, 2013). "We found that gastric cancer cell–conditioned media stimulated fibroblasts to produce IL-6, but we did not identify the specific molecules in the media responsible for this stimulation." (PMID 23593346, 2013). "To analyze further how fibroblasts promote tumor progression through IL-6 signaling, we examined the expression of STAT3–related genes by qRT-PCR in gastric cancer cell line NUGC4 when co-cultured with fibroblasts with or without neutralizing anti-IL-6 receptor antibody (MRA)." (PMID 23593346, 2013). "It remains unclear whether increased IL-6/STAT3 activation correlates with aberrant immunity in the progression and invasion of gastric cancer." (PMID 24116074, 2013). "Similarly, the expression of IL-6, surviving and VEGF was also highly increased in gastric cancer tissues as compared to those in adjacent normal mucosa." (PMID 24116074, 2013). "Similarly, the percentage of IL-6, surviving, and VEGF expression was significantly increased in higher TNM stage as compared to low TNM stage of gastric cancer." (PMID 24116074, 2013). "Comparison of serum cytokine levels of IL-6,IL-10 and VEGF in gastric cancer patients." (PMID 24116074, 2013). "Furthermore, the expression of IL-6, survivin, STAT3, STAT3 phosphorylation (p-STAT3), and VEGF were determined in human gastric cancer and adjacent normal mucosa through Western blot and immunohistochemistry." (PMID 24116074, 2013). "To examine the mechanisms of IL-6 production by fibroblasts, we used ELISA analysis to measure IL-6 produced in normal primary human gastric fibroblasts cultured in vitro in the presence or absence of conditioned media from cultured gastric cancer cells." (PMID 23593346, 2013). "To further confirm the increased expression of STAT3, p-STAT3, IL-6, survivin and VEGF in gastric cancer tissues, we also performed western blotting to determine their levels using anti-STAT3, anti-phosphorylated STAT3 (Tyr705), anti-IL-6, anti-survivin, anti-VEGF antibodies, respectively." (PMID 24116074, 2013). "IL-6 and TNF-α were found to be expressed at high levels in human gastric cancer samples." (PMID 23117246, 2013). "In addition, IL-6/STAT3 signals including surviving and VEGF were significantly augmented in gastric carcinoma tissues as compared to adjacent normal mucosa." (PMID 24116074, 2013).
gastric cancer (continued). "Since there is an inverse relationship between RKIP and STAT3 expression in gastric cancer specimens, we evaluated whether STAT3 and its key regulator IL-6 affects pRKIP expression." (PMID 22662230, 2012). "The anti-inflammatory effects of FFKSIL may be related to IgA, IgM, IgG, IL-6 and TNF-α production and IL-2, IL-4 and IL-10 reduction in gastric cancer rats." (PMID 22728348, 2012). "In conclusion, we have shown that gastric cancer cell lines can be classified on the basis of the mechanism of STAT3 activation (induced by MET or IL-6) into distinct and non-overlapping subsets." (PMID 21730976, 2011). "On the other hand, we found that gastric cancer cells in which STAT3 is activated in the absence of MET activation secreted IL-6, and this cytokine then activated STAT3 through the JAK pathway." (PMID 21730976, 2011). "This clinical observation was supported by mechanistic studies in gastric cancer cell lines, tumor organoids, and xenograft models, demonstrating that sildenafil suppresses tumor growth by inhibiting PDE5, destabilizing c-MYC, and downregulating IL-6/JAK/STAT3 signaling." (PMID 41450924, 2025). "In addition to the anti-inflammatory effects of PF treatments by the inhibition of IL-1β, IL-6, and TNF-α on LPS-treated Raw264.7 cells, the current study shows that PF treatments decreased tumor volume and induced cytotoxicity in gastric cancer cells in vivo and in vitro." (PMID 38140352, 2023). "Interestingly, IL-6 and IL-1 incubation did not affect Rev-erbα protein levels in gastric cancer cells." (PMID 36618075, 2022). "IL-33 promotes the production of IL-6 and MMP-3 by the ERK1/2 signaling pathway and enhances tumor invasion and escape ability in human gastric cancer (GC) cell lines." (PMID 36291105, 2022). "DYNC1I1, the binding subunit of cytoplasmic dynein, could assist the cytoplasmic dynein-mediated transport of P65 to the nucleus, following which P65 could promote the expression of IL-6 and activate the STAT3 phosphorylation to promote the proliferation and metastasis of gastric cancer cells." (PMID 35002514, 2022). "IL-6, TNF-α, and PD-L1 may be attractive targets for gastric cancer treatment." (PMID 36140220, 2022). "Besides the higher levels inflammatory cytokines at the local area of infection by H. pylori, we also evaluated that concentration of inflammatory cytokines like IL-6 and TGF-β was raised in the general circulation predicting the aggressive nature of gastric cancer." (PMID 33569347, 2020). "Our previous study has shown that IL-6 could mediate the interaction between cancer-derived mesenchymal stem cells and neutrophils through STAT3 signaling pathway, which ultimately promotes gastric cancer cell migration and angiogenesis." (PMID 32632106, 2020). "Considering the importance of immunity in controlling tumor progression, we studied whether acupuncture and moxibustion can decrease gastric cancer marker Ca199 and proinflammatory factors IL-6 and CRP, which were intimately related with development of gastric cancer." (PMID 33144870, 2020). "This was accompanied by increased expression of a panel of “pro-invasive” genes including vascular endothelial growth factor (VEGF), Interleukin-6 (IL-6), and MMP-7 mRNA suggesting a mechanism whereby increased chemerin could increase the metastatic potential of gastric cancer cells." (PMID 31561459, 2019). "A randomized controlled trial in gastric cancer patients who had gastrectomies indicates that DEX, given intraoperatively, has potent immunomodulatory properties that are observed as improvement in the Th1/Th2 ratio and reduction in IL-6 and tumor necrosis factor (TNF)." (PMID 30537999, 2018). "However, following treatment with IL-6, the hUC-MSCs had no growth-promoting effect on the gastric epithelial cells and gastric cancer cells." (PMID 25483835, 2015).
gastric cancer (continued). "As we expected, mRNA levels of IL-6, NF-κB and VEGF in human gastric cancer tissue were all significantly increased compared to those in adjacent normal mucosa tissue samples (all P<0.001), suggesting that high NF-κB mRNA levels might be positively correlated with IL-6 mRNA levels." (PMID 23117246, 2013). "IL-6 secretion from fibroblasts stimulated with conditioned media from three different gastric cancer cell lines was significantly suppressed by IL-1RA but not by anti-TNFα, suggesting the involvement of IL-1 in the mechanisms of IL-6 secretion from fibroblasts stimulated by cancer cells." (PMID 23593346, 2013). "Furthermore, in gastric cancer cells, VPS35 expression is upregulated, and it positively regulates the proliferation and peritoneal metastasis of gastric cancer cells through integrin/FAK/SRC signalling-mediated IL-6/STAT3 pathway activation in a YAP-dependent manner." (PMID 40484931, 2025). "The elevated level of IL-6 prior to treatment and cycle 2 of the FLOT regimen might be a predictor of pathological response to NAC in locally advanced gastric cancer (GC) or gastroesophageal junction (GEJ) cancer." (PMID 38398148, 2024). "The effects of an IL-6 pre-treatment of hUC-MSC on their phenotype and function and how it could be related to gastric cancer progression have been studied through an animal model of gastric cancer in which animals were treated with hUC-MSC alone or pre-treated hUC-MSC." (PMID 35955703, 2022). "Moreover, gastric cancer-derived MSCs (GC-MSCs) are also able to promote angiogenesis when interact with BGC-823 and MKN-28 GC cell lines, inducing overexpression of pro-angiogenic factors, such as, VEGF, MIP-2, TGF-β1, IL-6, and IL-8 favoring tube formation." (PMID 32296643, 2020). "However, the role of CAFs and IL-6 in gastric cancer has not been well addressed." (PMID 28186964, 2017). "By contrast, another meta-analysis involving patients with gastric cancer, in which 8 out of the 9 included trials involved surgical patients, found no changes in CRP levels but a reduction in IL-6 levels." (PMID 35949598, 2022). "Similar to our results, a gastric cancer study found that neither G-CSF, GM-CSF, TGF-β, M-CSF, IL-1β, IL17A, IL-6, TNFα, IL10, IFNγ and IL22 were able to induce MC degranulation, while only adrenomedullin did." (PMID 32722549, 2020). "b Results from quantitative PCR analysis showing the expression of IL6 mRNA in CAF lysates with and without co-culture with gastric cancer cell lines MKN-45, MKN-28, and KATO-III." (PMID 30927911, 2019). "However, we also observed that, in patients with gastric cancer, but not in patients with other types of gastric neoplasms, the biochemical balance in the systemic levels of these ILs was abnormal and “shifted” in a way that seemed to strongly favor the action of IL-6." (PMID 26486258, 2015). "Our study found that 50 μM of DIM (corresponding to IC50 in gastric cancer cell lines) had almost no lethal effect on GC-MSCs, but could activate the NF-κB signaling pathway and increase the expression of CCL2, IL-6, IL-8, TGF-β." (PMID 33842314, 2021). "Since expression of IL-6 upregulates SOCS-1, which participates in the negative regulation of the JAK/STAT pathway, we further analysed the expression of SOCS-1 in these gastric cancer cell lines." (PMID 15354212, 2004).